MMP9 (matrix metallopeptidase 9)
Diseases named in the same sentence as MMP9 in open-access papers (continued):
Sharing a sentence is not in itself a finding about the gene and the disease.
ischemia (continued). "Both prolonged ischemia and r-tPA treatment markedly increased MMP-9 expression in the ischemic hemisphere (all p < 0.0001)." (PMID 39273389, 2024). "The study employed different time points after the induction of ischemia, specifically looking at changes in MMP-9 activity." (PMID 38255970, 2024). "The matrix metalloproteinase family member MMP-9 plays an important role in disrupting the blood–brain barrier following ischemia." (PMID 38102677, 2023). "Matrix metalloproteinase (MMP-9) is one of a set of hydrolase enzymes that are expressed in many severe conditions, including wounds, osteoarthritis, ischemia, and viral disorders." (PMID 37648727, 2023). "Authors reported that protein expression of dimeric MMP-9 forms was highly stimulated (about 8-fold) by ischemia, compared to the expression of MMP-2 (1.5-fold)." (PMID 35631351, 2022). "In our experiments, we observed elevated MMP2 and MMP9 expression after lung ischemia–reperfusion at the tissue level in three separate organisms: human, rat, and mouse." (PMID 35705936, 2022). "Mmp8 and Mmp9 became overexpressed very soon after coronary occlusion (6 h), peaking at day one of ischemia with a Log2FoldChange around 4 and returning to control levels at day seven of ischemia." (PMID 36555255, 2022). "In rodent experiments, rt-PA has been shown to aggravate ischemia-induced damage to the blood–brain barrier by enhancing the proteolytic activity of MMP-9." (PMID 35910391, 2022). "To initially explore the relationship of MMP2 and MMP9 with lung ischemia–reperfusion injury, we performed relevant bioinformatics analysis using the GEO database." (PMID 35705936, 2022). "The scavenging of ROS reduced the activation of MMP9 as well as ischemia-induced BBB damage and vasogenic edema." (PMID 32221863, 2021). "To analyze the signaling pathways that involved the JNK, CREB, MMP-9, and c-Fos proteins during ischemia and the Semax treatment, we used the results of genome-wide data clustering that were published previously by our research group." (PMID 34201112, 2021). "While aberrant NO and MMP-9 are well-established moderators of BBB damage during acute ischemia, our work has added pericytes as a site of convergence for these mechanisms." (PMID 33505320, 2020). "The altered proteins, including HSP72, HIF-1α, HO-1, MMP-9, and other ischemia-related mediators, are involved in significant biological functions associated with HIF-1α." (PMID 33162790, 2020). "When it comes to the protein expression, matrix metalloproteinase-9 (MMP-9) was detected to be downregulated in ischemia/reperfused brain with osthole at 100 mg/kg." (PMID 32028721, 2020). "Here, the effects of OCA on MMP-2 and MMP-9 activity in liver, bile and serum were evaluated after hepatic ischemia/reperfusion (I/R) injury." (PMID 32911524, 2020). "In conclusion, both redox-related MMP-2 and MMP-9 activation are critical to the function of EPCs for in vivo ischemia-induced angiogenesis." (PMID 30645596, 2019). "Our results indicate that rTMS reduces inflammation-related gene expression (IL1β, TNFα, MMP9, and TGFβ), as suggested using a pulsed electromagnetic field following ischemia." (PMID 31031599, 2019). "In adult rats, MMP-9 is upregulated 1–2 weeks post-ischemia, with inhibition during this period leading to increased injury and delayed recovery." (PMID 32038147, 2019). "During ischemia, MMP-9 disrupts the connection between astrocyte endfeet and endothelial cells by degrading basal lamina." (PMID 31291966, 2019). "As MMP9 is a critical factor regulating pericytes migration, the downregulation of MMP9 after post-conditioning inhibited pericytes migration after ischemia–reperfusion, and maintained the integrity of BBB structure and function." (PMID 31824267, 2019).
ischemia (continued). "MMP-9 activation is crucially involved in ischemia/reperfusion injury by modulating extracellular matrix turnover, by triggering inflammatory cell migration and pro-inflammatory mediator release and the stimulation of angiogenesis." (PMID 30112663, 2018). "Our studies revealed that the beneficial effects of MSC on BBB after ischemia were due to the decrease of MMP-9 expression in neutrophil cells." (PMID 29724240, 2018). "We made a similar observation in a hind limb ischemia model, where MMP-2 and MMP-9 activity were decreased in Poldip2+/− mice when compared to Poldip2+/+ mice 21 days after ischemia." (PMID 29452577, 2018). "MSCs exerted a potent regulating function on endothelial ICAM-1 expression, which consequently attenuated neutrophil infiltration, MMP-9 function, and ischemia-induced BBB disruption." (PMID 29724240, 2018). "In accordance with other studies, our data showed that protein levels of MMP-2 and MMP-9 were induced in an ischemia time-dependent manner, and this change was accompanied by the loss of TJPs occludin and claudin-5." (PMID 29850586, 2018). "Increased BBB permeability induced by leukocyte-derived MMP-9 has been shown to correlate with peak neutrophil infiltration in ischemia-reperfusion injury." (PMID 29724240, 2018). "It is also reported that MMP-9 is upregulated after ischemia and influences the delayed BBB opening which contributes to the irreversible increase in BBB permeability." (PMID 28690765, 2017). "The results of the current study showed a significant increase in the expression of MMP-9 mRNA in the retina following 60 min of ischemia plus 24 h of reperfusion, which was consistent with the results of a recent report." (PMID 27617027, 2016). "Matrix metalloproteinase-9 (MMP-9) activity in the bone marrow of critical ischemia patients is reduced accompanying a reduced circulating and bone marrow resident CD34+ cell number." (PMID 26697131, 2016). "It is well known that MMPs are secreted into the extracellular space, as inactive zymogens, and successively activated; in particular, MMP-9 appears to be activated during ischemia." (PMID 27445688, 2016). "The ischemia-associated increases in P-p38 and MMP-9 protein levels were also attenuated by 0.5 mM SB203580 (P-p38 MAPK: 1.12 ± 0.18 vs. 0.18 ± 0.07, P < 0.001; MMP-9: 0.70 ± 0.23 vs. 0.21 ± 0.07, P = 0.002)." (PMID 27617027, 2016). "MMP-9 also plays an important role in ischemia-induced revascularization through the recruitment of macrophages." (PMID 26133989, 2015). "After ischemia/reperfusion, ex vivo tPA induced a significant increase in MMP-9 intensity in the supernatant of PMNs submitted in vivo to ischemia and G-CSF treatment (P <0.05)." (PMID 24885160, 2014). "Tissue reorganization requires activation of matrix metalloproteinases (MMPs) and VEGF enhances MMP-9 activity of in vivo ischemia models and in vitro BBB models." (PMID 24551038, 2014). "Among MMPs, MMP-9 has been reported to be the most abundant inducible factor in the pathology of ischemia in several previous studies including our rabbit IR model." (PMID 25186151, 2014). "As expected, MMP-2 and MMP-9 levels were elevated in injured ipsilateral brain tissue in all ischemia and hemorrhage mice." (PMID 23408937, 2013). "Up-regulated MMPs, especially MMP-2 and MMP-9, have been detected following acute kidney injury, mostly in animal models of ischemia, and up-regulation of MMP-9 was reported to protect from apoptosis in AKI." (PMID 22509332, 2012). "During ischemia, expression of inactive proMMP-9 increased significantly, a small portion of which was processed to active MMP-9, which manifests the pathological consequences of ischemia." (PMID 22587708, 2012). "Here, we demonstrated that brain MMP-9 was up-regulated in an embolic model after ischemia in both male and female mice." (PMID 22177314, 2011).
ischemia (continued). "In this regard, it has been proposed that early microglial expression of MMP-9 in the CA1 of rats after global ischemia, contributes to early neurodegeneration in this area." (PMID 21799862, 2011). "Among the main differences between their molecular pathways, MMP-2 is constitutively expressed, while MMP-9 can be stimulated at the level of gene activation by multiple stimuli including ischemia." (PMID 16846501, 2006). "Studies in rat, mouse, and baboon models have shown that MMP-9 is up-regulated following transient focal ischemia." (PMID 16078993, 2005). "Intravenous injection of anti-HMGB1 monoclonal antibody significantly protected rats from ischemia-induced blood–brain barrier disruption, which was associated with inhibiting the expression of proinflammatory factors like iNOS, TNF-α and MMP9 and microglial cell activation." (PMID 38740617, 2025). "Within the 7 days post-ischemia, MMP-9 activity returned to the level observed in sham animals." (PMID 38255970, 2024). "Some scholars proposed that hyperglycemia may aggravate ND, exacerbating blood-brain barrier dysfunction after ischemia-reperfusion injury by increasing oxidative stress and matrix metalloproteinase-9 (MMP-9) activity." (PMID 38310555, 2024). "Therefore, it is possible that in right-hemisphere stroke patients, ischemia-dependent activation of MMP-9 promotes neuroplasticity." (PMID 38891934, 2024). "The release of matrix metalloproteinases (MMP-9) by neutrophils, reaching the site of ischemia, both pre- and post-thrombolysis, worsens local injury and may attract more of these cells to the ischemic region." (PMID 39728061, 2024). "MMP-9 was consistently increased with the duration of ischemia." (PMID 39273389, 2024). "Another mechanism for the protective role of PC on female animals in this study could be attributed to reduction of post-ischemia inflammation, because, we observed a diminished level of MMP-9 in the PC+tPA group which may be an indicator of inflammation." (PMID 35432799, 2021). "Another culprit could be matrix metalloproteinase-9 (MMP-9) since suppressing its secretion in pericytes prevented degradation of the vascular basal lamina post ischemia." (PMID 34046769, 2021). "In addition, the COX-2 inhibitor CAY10404 reduces BBB injury after ischemia damage by decreasing MMP-9 activity and neutrophil infiltration." (PMID 34898370, 2021). "S-nitrosylation of MMP-9 has been shown to play a role in neuronal cell death, and may therefore also be involved in the rapid induction of MMP-9 by pericytes during microvascular ischemia." (PMID 33505320, 2020). "Following photothrombotic occlusion of superficial cortical capillaries in mice, it was demonstrated that ischemia resulted in rapid activation of matrix metalloproteinase-9 (MMP-9) and plasma leakage at places where pericyte somata adjoined the capillary wall." (PMID 32848875, 2020). "From this evidence we speculate that a post-translational modification of MMP-9 by NO may be one of the key mechanisms of pericyte-associated BBB breakdown during ischemia." (PMID 33505320, 2020). "Studies using ischemic rodent models demonstrated that there is a significant increase in the expression of pro/active MMP-9 within 24 h following ischemia in rats, and they have been detected in both central and peripheral cells with a unique expression profile." (PMID 31291966, 2019). "Importantly, PCB treatment abolished MMP-2 and MMP-9 induction in the ischemic tissue of t-PA-treated rats following 2 to 8 hr ischemia." (PMID 29850586, 2018). "This study suggested that baicalin could inhibit MMP-9 expression and MMP-9-mediated occludin degradation and thus protect from ischemia injury in MCAO model." (PMID 29344420, 2017). "Furthermore, a recent study demonstrated that inhibitors of Cox-2 decrease the expression of active-MMP-9 in neuronal and endothelial cells and prevent edema formation in the brain after ischemia." (PMID 27642277, 2016).
ischemia (continued). "In addition to the induction of pro-inflammatory factors, NF-κB also increases the secretion of MMP-2 and MMP-9, whose levels are increased in the reperfused myocardium after ischemia." (PMID 25084093, 2014). "Moreover, chemical activation of pro-MMP-9 zymogen by NO was reported in ischemia after t-PA dependent production." (PMID 23940734, 2013). "BDMC have also been suggested to be an important source of MMP-9 in the brain after ischemia." (PMID 23565108, 2013). "The data indicated that early exercise significantly inhibited the ischemia-induced reduction of occludin, and an increase in MMP-9 promoted TIMP-1 expression (p < 0.01), attenuated the BBB disruption (p < 0.05) and neurological deficits (p < 0.01) and diminished the infarct volume (p < 0.01)." (PMID 23708107, 2013). "Endothelium, glia, and neurons have been shown to display MMP-9 immunoreactivity after ischemia." (PMID 23565108, 2013). "In addition, MMP-9 deletion was reported to mitigate vascular lesions (hence insult) after ischemia." (PMID 22509332, 2012). "MMP-9 has been shown to play a critical role in the process of ischemia-induced EPC mobilization." (PMID 22848429, 2012). "Importantly, we describe an innovative technique by which the increase in MMP-9 levels can be imaged in-situ within the first few hours of ischemia reperfusion using NIR fluorescent imaging and an activatable optical probe MMPSense750." (PMID 22742423, 2012). "Our combined immunohistochemistry and Western blotting data strongly suggest that the integrin survival signaling pathway is disrupted in RGCs as a result of ischemia, and correlates with MMP-9 up-regulation, subsequent laminin degradation, and RGC apoptosis in the RIRI model." (PMID 23118988, 2012). "Moreover, many drugs or substances have been proven to attenuate the elevated levels of MMP-9 after ischemia and reduce the damage of cerebral ischemic." (PMID 20514206, 2009). "Recently, many drugs, such as tetracycline derivatives, cyclooxygenase inhibitors, ACEI inhibitors and AT1 receptor blockers, etc., have been found to attenuate the elevated expression levels of MMP-9 after ischemia and to reduce the damage of cerebral ischemic." (PMID 20514206, 2009). "Indeed, a recent study has shown that prevention of neutrophil infiltration significantly reduces MMP-9 up-regulation in an occlusion/reperfusion model of ischemia." (PMID 16078993, 2005). "While there were significant increases in gelatinase (MMP-2 and MMP-9) expression and activity and edema formation associated with ischemia, neutrophil depletion failed to cause any change." (PMID 16078993, 2005). "Furthermore, in primary astrocytes exposed to oxygen-glucose deprivation/recovery (a model mimicking ischemia), millimolar concentrations of carnosine reversed the expression of matrix metalloproteinase-9 (MMP-9), promoting axonal regrowth in astrocyte-neuron co-cultures." (PMID 41527663, 2025). "If they are indeed the source of rapid MMP-9 activation during ischemia, their pathological contributions to BBB damage may be significant, widespread, and readily overlooked by other biochemical approaches lacking spatiotemporal resolution to resolve the process." (PMID 33505320, 2020). "Since we did not detect MMP-9 in zymogen form in the plasma during the first hour of ischemia, it is less likely that serine proteases entering upon reperfusion would convert appreciable amounts of zymogen MMP-9 into its active form, though serine proteases may stimulate further MMP release." (PMID 22479334, 2012). "Also a finding demonstrated pro-MMP-9 expression was significantly increased in ischemic regions compared with corresponding contralateral regions after 2 hours of ischemia and remained elevated until 24 hours and activated MMP-9 was observed 4 hours after ischemia." (PMID 20514206, 2009).
ischemia (continued). "Intracoronary administration of the Doxy, ML-7, and L-NAME mixture during ischemia led to a decrease in MMP-2 (p = 0.0134), MMP-9 (p = 0.017), MLC1 (p = 0.003), and BNP-26 (p = 0.002) concentrations in the blood as compared to the MI." (PMID 38672140, 2024). "MMP-9 activity decreased in the MAP3 nanofiber group than in the control nanofiber and ischemia groups (p<0.01, p<0.05)." (PMID 38768136, 2024). "Specifically, it may be that the administration of CD147-blocking antibody before ischemia has a deleterious effect by suppressing the PC-induced facilitation of lactate release from astrocytes, whereas its administration after ischemia provides neuroprotection by inhibiting MMP-9 production." (PMID 38604775, 2024). "Within the post-ischemia setting, NGAL acts to enhance MMP-9 activation by forming the stable NGAL/MMP-9 complex which, in turn, can amplify and prolong ECM degradation during infarct remodelling." (PMID 37594719, 2024). "The duration of ischemia and r-tPA treatment also significantly increased MMP-2 expression (p < 0.01–0.001) in the ischemic hemisphere (p < 0.01) but to a lesser degree than MMP-9." (PMID 39273389, 2024). "The right atrial activity of reperfused myocardium was followed, showing a rapid increase in MMP2 and MMP9 activity accompanied by a rapid decrease in TIMP1, demonstrating global alteration of left ventricular function and persistence of ischemia." (PMID 37512106, 2023). "In ischemia, adipocyte fatty acid‐binding protein enhances JNK/c‐Jun activation to promote MMP‐9 transactivation in peripheral monocytes (macrophages and microglia), accelerating the breakdown of the BBB." (PMID 37452512, 2023). "Activation of matrix metalloproteinases (MMPs) in the brain after ischemia has been reported, including increased expression of constitutive enzymes (MMP-2) and inducible enzymes (MMP-9)." (PMID 32796743, 2020). "Our findings also showed that GLN administration led to higher HIF-1, MMP-9, and VEGF expressions at the late phase of ischemia in affected muscles." (PMID 32104148, 2020). "Astrocytes activated by ischemia and anoxia secrete many pro- and anti-inflammatory factors, such as IL-1β, IL-6, TNF-α, TGF-β, VEGF-A, MCP-1 CXCL-1, MMP-2, and MMP-9, which influence BBB integrity." (PMID 31779652, 2019). "Compared with MMP‐9, the expression of MMP‐2 lagged behind and peaked on the fifth day after ischemia." (PMID 31566928, 2019). "Overexpression of MMP-2 and MMP-9 can digest basal lamina, and this digestion begins as early as 2 h following ischemia, which corresponds with BBB breakdown 3 h following ischemia." (PMID 31291966, 2019). "It was reported that active MMP-9 induced the decrease of ZO-1 expression and degradation of ZO-1 was attenuated in MMP-9 knock-out mice after ischemia." (PMID 30088235, 2018). "For instance, HIF-1α regulation of aquaporin-4 (AQP-4) and matrix metalloproteinase-9 (MMP-9) lead to edema and blood brain barrier (BBB) disruption during ischemia." (PMID 29045486, 2017). "A greater decrease of MMP9 and LCN2 gene expression was seen in the IBT group during total ischemia (p = 0.003 and p = 0.018)." (PMID 27808277, 2016). "Macrophage MMP-9 expression affects vascular remodeling in other settings, including VEGF-induced angiogenesis in adult murine brains and ischemia-induced angiogenesis in skeletal muscle." (PMID 26406902, 2015). "Activated MMP-9 degrades the neurovascular matrix, and tPA amplifies total levels of MMP-9 after ischemia." (PMID 23565108, 2013). "Numerous studies identify a role for MMP-9 in the mechanisms of compromise of the BBB, epileptogenesis, or synaptic remodeling after ischemia or traumatic brain injury." (PMID 22507553, 2012). "In this study, we showed that zoledronate attenuated blood flow recovery and reduced ischemia-induced neovascularization by downregulating EPC mobilization and resulted in a reduction in tube formation by attenuating the activity of MMP-9, eNOS, and Akt." (PMID 22848429, 2012).